MMP9 (matrix metallopeptidase 9)
Diseases named in the same sentence as MMP9 in open-access papers (continued):
Sharing a sentence is not in itself a finding about the gene and the disease.
cancer (continued). "The proteolytic activity of MMP9 was indicated as a key component of the regulation of cancer-related cell–cell and cell–ECM interactions by MMP9-dependent processing of E-cadherin and integrins and promoting EMT processes." (PMID 35406619, 2022). "CXCL8, a chemokine in the CXC family, can stimulate the growth of HCC cells directly, mediate angiogenesis in the microenvironment, and recruit neutrophils to secrete matrix metalloproteinase 9 (MMP-9), thereby inducing the infiltration of cancer cells." (PMID 36531059, 2022). "The high expression of MMP-9 is closely related to the development, invasion, and metastasis in many cancers." (PMID 35178444, 2022). "Increased expression of MMPs has been associated with a poor prognosis of aggressive cancer, especially MMP-2 and MMP-9." (PMID 36605288, 2022). "Neutrophil-derived MMP9 has a role in migration through basement membrane, vessel angiogenesis, and cancer progression." (PMID 36400876, 2022). "MMP-9 Western blot assay detected bands that correspond to proMMP-9 and aMMP-9; interestingly, these bands showed high intensity in samples from cancer patients at stage IV compared to control subjects." (PMID 36213817, 2022). "Thereby, MMP2 and MMP9 can stimulate cell proliferation and angiogenesis and have been attributed a role in early-stage tumorigenesis and cancer progression." (PMID 36013233, 2022). "We also examined the expression of MMP-2 (Gelatinase A, or 72kDa Type IV Collagenase), another collagenase that is usually elevated together with MMP-9 in pathological conditions, including cardiac remodeling and cancer metastasis." (PMID 36432152, 2022). "MMP-9 is related to immune infiltration in pan-cancer and can be used as a biomarker related to cancer prognosis and metastasis." (PMID 35178444, 2022). "With the development of an appropriate delivery vehicle, the prospect of RNAi usage for MMP9 as cancer therapeutics in clinical trials seems probable." (PMID 35406619, 2022). "MMP2 and MMP9, as the two most important members of the matrix metalloproteinases, play a crucial role in promoting cancer metastasis." (PMID 35783013, 2022). "MMP-9 can dissolve in type-IV collagen, leading to damage to basement membranes, and has a very important role in the metastasis of cancer cells." (PMID 36352378, 2022). "Niclosamide treatment limited the invasion and migration of UM cells, decreased MMP-9 protein expression, and suppressed the NF-κB and Wnt/β-catenin signaling pathways, indicating its strong anti-cancer properties." (PMID 35457074, 2022). "In our study, this inhibitory activity on HepG2 cancer cells was supported by an inhibition in the expression MMP-9, VEGFR2 and EGFR." (PMID 36284117, 2022). "Other studies have shown that MMP-9 is highly expressed in cancer tissues such as oral cancer, GC, CRC, breast cancer, and cervical cancer, and has been used as a potential marker of cancers." (PMID 36246294, 2022). "MMP-9 is expressed abundantly in malignant tumors and contributes to cancer invasion and metastasis." (PMID 35127957, 2022). "It was therefore revealed that the decreases in cancer cell migration and invasion caused by Stellettin B are associated with downregulation of the activities and protein expressions of MMP-2 and MMP-9." (PMID 36483979, 2022). "The upregulation of p38MAPK by SNCG leads to increased MMP-9 expression, which promotes cancer cell invasion." (PMID 35637967, 2022). "MMPS is zinc-dependent endopeptidases that degrade essentially all extracellular matrix components, with MMP-2 and MMP-9 playing a role in the migration and invasion of cancer." (PMID 36276736, 2022). "MMP2 and MMP9 are two special subtypes of MMPs, which have been deeply studied in cancer metastasis in recent years." (PMID 35178453, 2022).
cancer (continued). "MMP9 is a key protein that plays key role in cancer cells invasion, which serves as a prognostic biomarker in certain cancer patients, implying its potential role as a therapeutic target." (PMID 35186766, 2022). "Development of angiogenesis around several cancers is closely related to the expression of chymase and MMP-9, and postoperative survival curves have revealed that patients with a higher number of chymase positive cells have lower survival rates." (PMID 36289761, 2022). "Although these new approaches hold promise due to enhanced selectivity toward MMP9, the clinical utility of these compounds as therapeutic agents in cancer remains to be investigated." (PMID 35158891, 2022). "In this study, we obtained the expression levels of MMP-9 and the prognosis and relevant indices of 33 cancer types from TCGA database." (PMID 35178444, 2022). "Although MMP9 is generally known to enhance cancer progression, it is well established that MMP9 can also function as an inhibitor of cancer growth and metastasis." (PMID 35406619, 2022). "On the other hand, it is known that IL-8 induces MMP9 expression and secretion in cancer cells, which positively correlates with their metastatic potential." (PMID 35406619, 2022). "Both MMP2 and MMP9 are extensively studied for cancer metastasis in a large variety of experimental as well as clinical cancer models, therefore, inhibiting, MMPs is suggested to combat cancer." (PMID 32761892, 2022). "The nanofibers were characterized in terms of size, morphology, surface charge, uptake by cancer cells, the release of Doxo in the presence of active MMP-9, and the related cytotoxicity." (PMID 35893800, 2022). "In the present study, MMP9 was proven to be downregulated in GA-Me-treated cancer cells compared to untreated cancer cells, consistent with our previous study." (PMID 35574354, 2022). "The MAPK pathway is a prominent mechanism for coordinating transcription factors that are activated by ERK kinase to modulate downstream MMP-2 and MMP-9 genetic expression and afterward elevate cancer onset and development." (PMID 35860597, 2022). "The up-regulator of cell proliferation and CAF-derived collagen triple helix repeat containing-1 have also been recognized as genes that promote cancer cell invasion induced by MMP-9 overexpression." (PMID 36422541, 2022). "Based on our analysis, MMP-9 has the potential to be a significant biomarker for cancer in hypertensive patients." (PMID 35742125, 2022). "Tested treatments resulted in a significant decrease in the relative expression of MMP-9 ranging from 0.9 to 0.1 fold in HepG2 cancer treated cells; the most pronounced effect was recorded in case of sorafenib-ramucirumab combination (0.1 fold)." (PMID 36284117, 2022). "Because of the important role of MMP-9 in tumorigenesis, it has been postulated to be a good prognostic marker and has been considered an attractive target in cancer therapy." (PMID 35463960, 2022). "In this study, MMP-9 expression was associated with TMB in eight cancer types and with MSI in six cancer types." (PMID 35178444, 2022). "As lower pH in cancer cells is known to facilitate cancer cell invasion, we checked the effect of MMP9 inhibitor and glycolysis inhibitor, 2DG on cancer cell invasiveness." (PMID 35686673, 2022). "SIRT6 and MMP-9 expression in cancer tissues was significantly higher than in paired normal breast tissues." (PMID 35840633, 2022). "Our results showed that the expression of MMP2 and MMP9 was reduced with Rab31 knockdown, decreasing the capability of cancer cells to metastasize." (PMID 34975321, 2022). "Our results also showed that MMP-9 has a significant positive correlation with TMB in a variety of cancers." (PMID 35178444, 2022).
cancer (continued). "Secretion of MMP-2 and MMP-9 was shown to break down the basement membrane and promote lymph node invasion and cancer metastasis, thus leading to poor prognoses." (PMID 36226250, 2022). "Neutrophil NE and matrix metalloproteinase 9 (MMP9), through proteolytic cleavage and remodeling of laminin, induced cell cycle progression in previously dormant cancer cells." (PMID 35979369, 2022). "We observed the elevated expression of fibronectin, vimentin, MMP-9, and N-cadherin with a parallel reduction in the levels of occludin and E-cadherin in the untreated cells indicating that the tested cancer cells present mesenchymal-like characteristics." (PMID 35883447, 2022). "Its gelatinase inhibitory features suggested that it can be used in pathologies related to enhanced gastrointestinal MMP-9 activity, namely cancer, and inflammatory diseases." (PMID 36551666, 2022). "MMP2 and MMP9 expression in metastatic cancer cells is often elevated and they are considered of particular importance in developing metastatic potential, particularly in tissues where ECM is abundant in collagen type IV." (PMID 36143328, 2022). "In the PPI network, the core targets, including AKT1, CREB1, CDC42, SIRT1, PIK3CA, and MMP9, are key cancer‐related genes, which further indicate the important role of miR‐204‐5p in human cancers." (PMID 35908280, 2022). "Due to their ability to degrade the essential elements of basement membranes, MMP2 and MMP9, also known as gelatinase A and gelatinase B, are thought to be the significant MMPs involved in the invasion and metastasis of several cancers." (PMID 36430837, 2022). "Matrix metalloproteinase 9 (MMP9) has been widely found to link to the pathology of cancers, such as invasion, metastasis and angiogenesis." (PMID 35912006, 2022). "This resulted in the upregulation of MDR1 gene, metalloproteinase inducer (CD147) and matrix metalloproteinases (MMP2 and MMP9), which are highly associated with the cancer cells invasiveness and migration, and MDR in cancer." (PMID 36233276, 2022). "Fibroblast growth factor receptor 1 is involved in the regulation of FAK phosphorylation and MMP‐9 expression via the FGFR‐extracellular regulated kinase‐FAK pathway, which has been implicated in the invasion, metastasis, and motility of cancer cells." (PMID 34913237, 2022). "It is well known that high expression of MMP-9 is important for the invasive phenotype of cancer cells." (PMID 35563563, 2022). "The results of this study suggested that LCN2, SLC22A17, and MMP9 genes interact with each other, indicating their synergic involvement in cancer." (PMID 36211450, 2022). "Previous studies have demonstrated that MMP-9 plays an important role in the migration of cancer cells such as MDA-MB-231." (PMID 35204811, 2022). "MMP9 is a matrix metalloproteinase that aids cancer infiltration, metastasis, as well as angiogenesis." (PMID 36059672, 2022). "MTX-treatment also induced the expression of the collagenase MMP9, an enzyme which is involved in the degradation of the extracellular matrix during cancer cell invasion." (PMID 35577770, 2022). "Cancer-associated adipocytes (CAA) also secrete various cytokines, chemokines, hormonal factors, and MMPs (MMP-9) that enhance TME interactions and promote matrix degradation and metastasis." (PMID 35205204, 2022). "In contrast, volatile agents have been shown to reduce ECM breakdown through the down-regulation of Matrix metalloproteinase 9 (MMP-9), thus reducing the metastatic cancer cell potential." (PMID 36143832, 2022). "MMP-9 overexpression has been observed in a variety of malignant cancers and has been extensively studied as a potential biomarker for several cancers." (PMID 35463960, 2022). "To determine the differences in the expression levels of MMP-9 in various human cancers, we examined the MMP-9 expression levels using the RNA-seq data of multiple malignancies from TCGA database." (PMID 35178444, 2022).
cancer (continued). "TAMs induce EMT process of cancer cells by producing MMP-9 and activating PI3K/AKT/SNAIL signaling pathway, ultimately leading to severe metastasis of gastric cancer." (PMID 36611857, 2022). "MMP2 and MMP9 were EMT-related genes which were closely related to the invasion or metastasis of cancer." (PMID 35043728, 2022). "MMP-9 is found to play a crucial role in gastric cancer, breast cancer, colorectal cancer, non-small-cell lung cancer, ovarian cancer, and many other cancers." (PMID 35463960, 2022). "Previous studies have showed that WNT/β-catenin pathway inhibition has the potential to reduce cancer invasion and metastasis via regulating involves NF-κB/MMP-9 mediated EMT process." (PMID 35484165, 2022). "GM-CSF, TNF-α, MMP- 2, MMP-9, and proinflammatory cytokines like IL-1β and IL-6 are involved in cancer progression mediated by NF-κB and AP-1." (PMID 35127957, 2022). "Intermolecular interactions of DATS and DOXO against numerous cancer targets by molecular docking indicated MMP-9 as the most favourable target for DATS exhibiting binding energy of −4.6 kcal/mol." (PMID 35408590, 2022). "We investigated the effects of SIRT6 on protein kinase C activator- and cytokine-mediated cancer cell invasion and migration in MCF-7 and MDA-MB-231 cells and the association between SIRT6 and matrix metalloproteinase-9 (MMP-9) expression." (PMID 35840633, 2022). "Although some saponins (Notoginsenoside R1, Ginsenoside Rg1, Rh1 etc.)have been reported to suppress MMP-9 activity in cancer cell lines, a comprehensive screening of PNG targeting MMP-9 is still lacking." (PMID 36432152, 2022). "As the main family members of MMPs, MMP2 and MMP9 play an important role in the invasion and metastasis of cancer cells." (PMID 35468097, 2022). "Matrix metalloproteinase (MMP) family proteins, such as MMP2 and MMP9, are of vital importance in cancer metastasis, and MMPs are highly expressed in cancers." (PMID 35646704, 2022). "During the development of cancer, due to its capacity to degrade extracellular protein components, MMP9 is involved in the removal of physical barriers to cell migration." (PMID 36408222, 2022). "Whereas MMP-9 is highly upregulated in most types of cancer, MMP-2 expression only modestly increases." (PMID 36539774, 2022). "Because of its correlation with diseases, such as ulcerative colitis and colorectal cancer, MMP9 has been detected as a biomarker in numerous diseases including cancer and believed to be a potential target for therapeutic intervention." (PMID 35255869, 2022). "Relevant mechanistic studies have shown that DDB2 decreases NF-κB activity and the expression of matrix metalloproteinase 9 (MMP9) by upregulating IκBα gene expression, limiting cancer cell invasiveness." (PMID 36190612, 2022). "Further research revealed that H3K4 methyltransferase is recruited by MKL1, which potentiates cell migration and invasion through matrix metallopeptidase 9 in cancer." (PMID 34761735, 2022). "This was explained by the upregulated levels of matrix metalloproteases (MMP-2 and MMP-9) under microgravity, thus playing a crucial role in cancer invasion and migration." (PMID 36613598, 2022). "The action of TIMP-1 is achieved via reduction of collagen-degrading enzymes, MMP-2 and MMP-9, that promote cancer cell invasiveness." (PMID 36291926, 2022). "MMP-9 shRNA is a short hairpin RNA responsible for cancer metastasis, while miR-21i is an inhibitor of miR-21 with the capability for preventing cancer cell growth." (PMID 35743245, 2022). "Treatment with Iso at both concentrations results in a decrease in proteolytic activity, demonstrated by accumulation of MMP9 proteases in cancer cells, and also by decreased proteolytic fractions of 72 kDa (proMMP2) and active MMP2 (66 kDa)." (PMID 36500428, 2022). "MMP9 can induce extracellular matrix degradation, thereby reducing the stability of cancer cells and making them more prone to invasion and metastasis." (PMID 35566048, 2022).
cancer (continued). "Increased expression of matrix metalloproteases (MMPs) is a characteristic of cancer cells undergoing invasion, and in this study, we found higher levels of MMP9 that have been documented to be regulated by higher SIRT6 status in cancer cells." (PMID 35686673, 2022). "Among the MMPs, MMP2 and MMP9 are activated upon secretion and are considered to be the most relevant to cancer migration and invasion." (PMID 35223210, 2022). "Here, we review the current understanding of MMP9, its regulation and biochemical properties, and its role in cancer progression." (PMID 35406619, 2022). "According to the literature, MMP9 expression seems to require the direct co-culture of fibroblasts with cancer cells and a 3D culture system, in opposition to the monolayer cultures used in our study." (PMID 36010567, 2022). "Here, we systematically studied MMP-9 expression and its correlation with prognosis and metastasis in 33 cancer types to help us fully understand the role of MMP-9 in tumors." (PMID 35178444, 2022). "Cancer cell invasion and metastasis is assisted by activities of MMP-2 and MMP-9 which are associated with promoting cell-cell and cell-matrix interactions during the EMT." (PMID 36147907, 2022). "Plumbagin was shown to be able to inactivate the major pathways involved in cancer cell expansion including Akt/NF-kB, MMP-9, and VEGF pathways, which will prevent the development of cancer." (PMID 36463191, 2022). "A new tryptophan metabolite, 5-methoxytryptophan (5-MTP), was found to reduce COX-2-mediated cancer cell proliferation and migration by inhibition of COX-2 expression, and to reduce cancer cell invasion by inhibition of MMP-9 expression." (PMID 36232383, 2022). "We found that the overexpression of miR-641 expression led to significant decreases in the protein expression levels of Cox-2, MMP-2, and MMP9, which were the crucial indicators of cancer metastasis." (PMID 35069784, 2022). "Members of the MMP family of proteins, particularly MMP2 and MMP9, play a crucial role in cancer metastasis." (PMID 35178352, 2022). "MMP-9 is related to immune infiltration in pan-cancer and can be used as a biomarker of cancer prognosis and metastasis." (PMID 36776395, 2022). "Of the compounds identified, trichoderminol, trichodermarin E, and trichodermol exhibited promising cytotoxicity against three cancer cell lines and inhibition of both MMP-9 gelatinolysis and LPS-induced NO production." (PMID 35200610, 2022). "Nevertheless, MMPs, especially the gelatinases MMP-2 and MMP-9, have a significant role in the development and progression of cancers, including those of the colon, lung, prostate, and breast." (PMID 35457074, 2022). "In fact, it is widely recognized that MMP-9 is synthesized by cancer cells regulating VEGF release promoting angiogenesis and spread of metastasis." (PMID 36290354, 2022). "MMP-9 has been found to be a potential cancer biomarker in several cancer types, such as non-small cell lung cancer, cervical cancer, pancreatic cancer, and metastasized breast cancers." (PMID 36242015, 2022). "Anti‐Chi3L1 antibody significantly decreased the expression of cancer growth and migration‐associated proteins, such as PCNA, cyclin D1, cyclin E, Cdk2, Cdk4, Cdk5, MMP2 and MMP9 in A549 lung metastasis model tissues." (PMID 34861103, 2022). "Matrix metalloproteinase-9 (MMP9) and urokinase-type plasminogen activator (uPA) play a regulatory role in cancer cell invasion, which would be associated with AMPK activation and NF-κB inhibition." (PMID 36557939, 2022). "MMP-9 is a neutrophil-derived protein that is known to facilitate cancer progression through extracellular matrix (ECM) degradation." (PMID 35267667, 2022). "Reportedly, the extracts of the fruit, stems, seeds, and twigs of A.muricata administered to fibrosarcoma cells (HT1080) inhibited matrix metalloproteinases (MMPs) such as MMP-2 and MMP-9, which play important roles in cancer progression." (PMID 35208993, 2022).